RNF182 (ring finger protein 182)
Description:
E3 ubiquitin-protein ligase that mediates the ubiquitination of ATP6V0C and targets it to degradation via the ubiquitin-proteasome pathway. Also plays a role in the inhibition of TLR-triggered innate immune response by mediating 'Lys'-48-linked ubiquitination and subsequent degradation of NF-kappa-B component RELA.
Synonyms: MGC33993
Tractability: Antibody: UniProt predicts a signal peptide or a membrane-spanning region.
Gene: Protein-coding gene on chromosome 6 (13,924,446 to 13,980,310, forward strand). Ensembl gene ENSG00000180537.
Subcellular location: Membrane; Cytoplasm
Subcellular location (Human Protein Atlas): Golgi apparatus; Nucleoplasm; Vesicles
Pathways (Reactome):
Immune System: Antigen processing: Ubiquitination & Proteasome degradation
Gene Ontology:
Molecular function: protein binding; ubiquitin protein ligase activity; ubiquitin-protein transferase activity
Biological process: protein ubiquitination
Cellular component: cytoplasm; membrane
Genetic constraint (gnomAD): Loss-of-function variants: 15 observed, 15.27 expected, observed/expected ratio (o/e) 0.98, 90% interval 0.66 to 1.51. The upper end of that interval is the gene's LOEUF score, 1.51, which puts it in group 6 of 6, group 1 being the genes least tolerant of losing a copy. Missense variants: 268 observed, 310.98 expected, observed/expected ratio (o/e) 0.86, 90% interval 0.78 to 0.95. Synonymous variants: 128 observed, 130.5 expected, observed/expected ratio (o/e) 0.98, 90% interval 0.85 to 1.14.
Homologues: Orthologues: chimpanzee RNF182 (100% identical), macaque RNF182 (99% identical), mouse Rnf182 (98% identical), rabbit RNF182 (98% identical), dog RNF182 (98% identical), rat Rnf182 (98% identical), guinea pig RNF182 (96% identical), pig RNF182 (96% identical), tropical clawed frog rnf182 (81% identical), zebrafish rnf182 (52% identical), Drosophila melanogaster roq (22% identical). Paralogues in human: RC3H1 (25% identical), RC3H2 (25% identical), RNF228 (19% identical), RNF227 (14% identical), RNF224 (13% identical).
Diseases named in the same sentence as RNF182 in open-access papers:
RNF182 is named in the same sentence as 19 diseases in open-access papers, as found by Europe PMC text mining. Sharing a sentence is not in itself a finding about the gene and the disease. The quoted sentences say what the papers report.
Alzheimer disease (3 papers, 2014 to 2022). A progressive, neurodegenerative disease characterized by loss of function and death of nerve cells in several areas of the brain leading to loss of cognitive function such as memory and language. "A previous study has indicated increased expression of the E3 ubiquitin ligase protein RNF182 in Alzheimer's disease brain." (PMID 24695574, 2014). "RNF182 was shown using in vitro studies to bind ATP6V0C with high affinity and target it for degradation, thus suggesting the potential for disruption of ATP6V0C function in Alzheimer's disease." (PMID 24695574, 2014).
asthma (2 papers, 2023). "Among these 9 feature genes, RNF182 had the best ability in distinguishing severe asthma, with AUC of 0.889 (GSE43696) and 0.849 (GSE63142), respectively." (PMID 36862916, 2023). "The results showed that these 9 feature genes had good discrimination ability for asthma, with age, RNF182 and ITGA10 being the top three contributing factors." (PMID 36862916, 2023). "The Venn diagram showed that there are indeed common DEGs between obesity and asthma, namely IL36RN, PHACTR3, SLAMF7, AKR1B10 and RNF182." (PMID 37723557, 2023).
lung adenocarcinoma (2 papers, 2022 to 2023). A carcinoma that arises from the lung and is characterized by the presence of malignant glandular epithelial cells. "This study examines the function of RNF protein 182 (RNF182) in lung adenocarcinoma (LUAD) cells and its impact on p65 and programmed death ligand 1 (PDL1) regulation." (PMID 37249301, 2023). "Next, Bap was prepared and used to treat HBE (normal lung epithelial cells) and A549 (lung adenocarcinoma) cells, and the results showed that treatment of the cells with Bap significantly downregulated mRNA expression of RNF182 in both HBE and A549 cells." (PMID 36686776, 2022).
Rett syndrome (2 papers, 2019 to 2020). A severe neurodevelopmental disorder affecting the central nervous system. "Since RNF182 possibly compromises brain function, it is speculated to be involved in postnatal neurodevelopmental abnormalities associated with Rett syndrome." (PMID 32486221, 2020). "Next, RNF182 was identified as a gene associated with Rett syndrome." (PMID 32486221, 2020).
tendinopathy (2 papers, 2022 to 2026). "Consistent with previous findings in tendinopathy, silencing RNF182 abolished the protective effect of FD, whereas RNF182 overexpression induced dose‐dependent p65 degradation." (PMID 41503854, 2026). "Previous work has shown that FD promotes p65 degradation through RNF182 in tendinopathy." (PMID 41503854, 2026). "Therefore, the targeted degradation of p65 by FR is closely related to p62 and RNF182, which provides a theoretical basis for applying FR in the treatment of tendinopathy and other inflammatory diseases." (PMID 35458235, 2022).
glioblastoma (1 paper, 2026). The most malignant astrocytic tumor (WHO grade IV). "Experiments using siRNA to inhibit RNF182 in the human glioblastoma cell line U87MG significantly reduced cell proliferation, suggesting that RNF182 promotes tumor growth and may be a potential therapeutic target." (PMID 42073544, 2026).
idiopathic pulmonary fibrosis (1 paper, 2023). Idiopathic pulmonary fibrosis (IPF) is a nonneoplastic pulmonary disease that is characterized by the formation of scar tissue within the lungs in the absence of any known cause. "In this study, we identified four potential biomarkers (FHL2, HPCAL1, RNF182, and SLAIN1) and evaluated the potential pathogenic role of SLAIN1 in idiopathic pulmonary fibrosis." (PMID 37783761, 2023). "In summary, this research successfully pinpointed four promising biomarkers (FHL2, HPCAL1, RNF182, and SLAIN1) and investigated the potential involvement of SLAIN1 in the pathogenesis of idiopathic pulmonary fibrosis." (PMID 37783761, 2023). "FHL2, HPCAL1, RNF182, and SLAIN1 were identified as biomarkers of idiopathic pulmonary fibrosis using LASSO logistic regression, RF, and SVM-RFE algorithms." (PMID 37783761, 2023).
lung carcinoma (1 paper, 2022). "Next, through K-M plotter analysis, we observed that low expression of RNF182 was associated with poor survival in LUAD patients (logrank P=4.3e-05) and lung cancer patients (logrank P=3.6e-07)." (PMID 36686776, 2022).
non-small cell lung carcinoma (1 paper, 2022). A group of at least three distinct histological types of lung cancer, including non-small cell squamous cell carcinoma, adenocarcinoma, and large cell carcinoma. "Here we reported that the carcinogen Bap suppresses the expression of ring finger protein 182 (RNF182) in non-small cell lung cancer (NSCLC) cells, which is mediated by abnormal hypermethylation in an AhR independent way and transcriptional regulation in an AhR dependent way." (PMID 36686776, 2022).
psoriatic arthritis (1 paper, 2021). Joint inflammation associated with psoriasis. "Several of those have been implicated in pro-inflammatory processes; for example, HLA-C has been associated with RA; RNF182 was previously reported to be over-expressed in RA, and TUBB2A was found to be over-expressed in psoriatic arthritis." (PMID 33461591, 2021).
sarcoidosis (1 paper, 2016). Sarcoidosis is a multisystemic disorder of unknown cause characterized by the formation of immune granulomas in involved organs. "Of those genes which were identified in only TB or sarcoidosis compared with healthy controls, only one (RNF182) was two-fold different between TB and sarcoidosis." (PMID 27706152, 2016).
tumor (4 papers, 2011 to 2026). "However, loss of the overlapping 6p21.2-p12 segment in tumour P9A was substantiated by MLPA analysis with the RNF182 probe." (PMID 21931686, 2011). "Next, we tested whether downregulation of RNF182 in tumor tissues was caused by DNA methylation." (PMID 36686776, 2022). "Here in this work, we validated decreased RNF182 expression in LUAD samples and figured out the link of low RNF182 expression to the advanced tumor stage of LUAD patients." (PMID 37249301, 2023). "In conclusion, this work defines a novel tumor‐suppressive E3 ubiquitin ligase RNF182 which induces ubiquitination and degradation of p65 and consequently suppresses the transcription of PDL1, therefore, alleviating immunosuppression and cancer development." (PMID 37249301, 2023). "Coordinating with the functional assay results that the RNF182 restoration blocked the proliferation, mobility, resistance to apoptosis, and tumorigenic activity of LUAD cells, we report that RNF182 plays a tumor‐suppressive effect on LUAD." (PMID 37249301, 2023). "Considering that the further p65 upregulation blocked the effects of RNF182 overexpression on LUAD cells, we opined that the p65 degradation is implicated in the tumor‐suppressive roles of RNF182." (PMID 37249301, 2023). "In conclusion, this study demonstrated that RNF182 functions as a tumor suppressor via suppressing NSCLC cells proliferation and inducing cell cycle arrest." (PMID 36686776, 2022). "Considering the important physiological functions and tumor suppressive effects of RNF182, further study of the upstream regulatory mechanism of RNF182 will undoubtedly be helpful to the treatment of NSCLC." (PMID 36686776, 2022). "Our findings suggested that RNF182 exerts a tumor suppressor effect in NSCLC through inhibiting cell growth and promoting cell cycle arrest that are key characteristics of cancer progression." (PMID 36686776, 2022). "This work defines a novel tumor‐suppressive E3 ubiquitin ligase RING finger protein 182 (RNF182) which induces ubiquitination and degradation of p65 and consequently suppresses the transcription of programmed death ligand 1, therefore, alleviating immunosuppression and cancer development." (PMID 37249301, 2023). "Specific upregulation of RNF182 may help reduce immune escape and limit tumor growth in LUAD, though much more preclinical research is required to validate our findings." (PMID 37249301, 2023). "RNF182 expression was significantly decreased in NSCLC tumor tissues." (PMID 36686776, 2022). "Moreover, we found that RNF182 expression is significantly downregulated in LUAD tumor tissues compared with that in matched adjacent tissues, and the downregulation of RNF182 is strongly correlated with poor prognosis in LUAD patients." (PMID 36686776, 2022). "Taken together, these observations revealed that RNF182 expression is inhibited in NSCLC tumor tissues and that its low expression in NSCLC patients is associated with poor clinical outcome, indicating that NSCLC progression is associated with RNF182 alteration." (PMID 36686776, 2022). "However, these tumor‐suppressive effects of RNF182 on LUAD cells were blocked by p65 restoration." (PMID 37249301, 2023). "Furthermore, RNF182 exhibits low expression and hypermethylation in tumor tissues." (PMID 36686776, 2022). "However, the specific mechanisms underlying the anti-tumor role of RNF182 have not been thoroughly elucidated to date, and further investigations are needed." (PMID 36686776, 2022). "This work reports that the restoration of RNF182 in LUAD results in increased immune activity and tumor suppression, which is ascribed to its regulation on the ubiquitination and degradation of p65 protein and the subsequent transcriptional inactivation of PDL1." (PMID 37249301, 2023). "Furthermore, RNF182 is inactivation and hypermethylation in NSCLC tumor tissues." (PMID 36686776, 2022).
cancer (3 papers, 2022 to 2023). A tumor composed of atypical neoplastic, often pleomorphic cells that invade other tissues. "The correlation of RNF182 with cancer development, to the best of we know, has barely been investigated." (PMID 37249301, 2023). "Benzo[a]pyrene (BaP), an AhR agonist not only increased nuclear accumulation of AhR, but also transcriptionally downregulated RNF182 in cancer cells." (PMID 37830596, 2023). "RNF182 knockdown considerably increased colony formation and proliferation of the cancer cells." (PMID 37830596, 2023). "Overexpression of RNF182 suppressed the PDL1 expression, increased the cytotoxicity in LUAD cells cocultured with CD8+ T cells, and suppressed the tumorigenesis of cancer cells in vivo." (PMID 37249301, 2023).
neurodegenerative disease (1 paper, 2023). A disorder of the central nervous system characterized by gradual and progressive loss of neural tissue and neurologic function. "If E3 proteins such as RNF182 and TRIM9, which are specifically expressed in the central nervous system, can be linked to target proteins, then it may be possible to develop therapeutic drugs for neurodegenerative diseases with minimal side effects." (PMID 36726375, 2023).
RNF182 also shares sentences with these, for which no sentence is quoted: hepatocellular carcinoma (2 papers); glioma (1); Obesity (1); prostate carcinoma (1); renal fibrosis (1).